PRM3 (protamine 3)
Description:
Protamines substitute for histones in the chromatin of sperm during the haploid phase of spermatogenesis. They compact sperm DNA into a highly condensed, stable and inactive complex (By similarity).
Tractability: No criterion of Open Targets' tractability assessment is met for any kind of drug.
Gene: Protein-coding gene on chromosome 16 (11,273,199 to 11,273,629, reverse strand). Ensembl gene ENSG00000178257.
Subcellular location: Nucleus; Chromosome
Gene Ontology:
Biological process: flagellated sperm motility
Cellular component: cytoplasm; chromosome; nucleus
Genetic constraint (gnomAD): Loss-of-function variants: 1 observed, 0.78 expected, observed/expected ratio (o/e) 1.29, 90% interval 0.3 to 1.91. That is too few expected variants to judge how well the gene tolerates losing a copy. Missense variants: 160 observed, 116.3 expected, observed/expected ratio (o/e) 1.38, 90% interval 1.21 to 1.57. Synonymous variants: 72 observed, 45.81 expected, observed/expected ratio (o/e) 1.57, 90% interval 1.3 to 1.88.
Homologues: Orthologues: mouse Prm3 (68% identical).
Diseases named in the same sentence as PRM3 in open-access papers:
PRM3 is named in the same sentence as 13 diseases in open-access papers, as found by Europe PMC text mining. Sharing a sentence is not in itself a finding about the gene and the disease. The quoted sentences say what the papers report.
prostate adenocarcinoma (1 paper, 2016). "Hence, a RT-PCR based approach was also used to clarify which promoters within the TBXA2R, namely Prm1 or Prm3, are regulating TPα and TPβ expression in human prostate tissue or in the prostate adenocarcinoma LNCaP and PC-3 cell lines." (PMID 27689401, 2016).
prostate neoplasm (1 paper, 2016). A neoplasm (disease) that involves the prostate gland. "Significant changes in the methylation landscape within the Prm1 and Prm3 regions of the TBXA2R were observed across a range of benign, precursor prostate neoplasms and increasing PCa staging." (PMID 27689401, 2016).
PRM3 also shares sentences with these, for which no sentence is quoted: adenocarcinoma (1 paper); asthenospermia (1); breast carcinoma (1); cancer (1); esophageal cancer (1); male infertility (1); oligospermia (1); proliferative inflammatory atrophy (1); prostatic intraepithelial neoplasia (1); toxoplasmosis (1); tumour (1).